MCFD2 (multiple coagulation factor deficiency 2, ER cargo receptor complex subunit)
Description:
The MCFD2-LMAN1 complex forms a specific cargo receptor for the ER-to-Golgi transport of selected proteins. Plays a role in the secretion of coagulation factors.
Synonyms: SDNSF; F5F8D; LMAN1IP; F5F8D2
Tractability: Antibody: UniProt predicts a signal peptide or a membrane-spanning region. PROTAC: ubiquitination databases record sites on it; its protein half-life has been measured.
Gene: Protein-coding gene on chromosome 2 (46,901,870 to 46,941,855, reverse strand). Ensembl gene ENSG00000180398.
Subcellular location: Endoplasmic reticulum-Golgi intermediate compartment; Endoplasmic reticulum; Golgi apparatus
Pathways (Reactome):
Vesicle-mediated transport: COPII-mediated vesicle transport; Cargo concentration in the ER
Metabolism of proteins: Transport to the Golgi and subsequent modification
Gene Ontology:
Molecular function: protein binding; calcium ion binding
Biological process: endoplasmic reticulum to Golgi vesicle-mediated transport
Cellular component: cargo receptor complex; endoplasmic reticulum-Golgi intermediate compartment membrane; endoplasmic reticulum membrane; ER to Golgi transport vesicle membrane; endoplasmic reticulum; endoplasmic reticulum-Golgi intermediate compartment; Golgi apparatus
Genetic constraint (gnomAD): Loss-of-function variants: 11 observed, 13.31 expected, observed/expected ratio (o/e) 0.83, 90% interval 0.52 to 1.37. The upper end of that interval is the gene's LOEUF score, 1.37, which puts it in group 5 of 6, group 1 being the genes least tolerant of losing a copy. Missense variants: 191 observed, 188.23 expected, observed/expected ratio (o/e) 1.01, 90% interval 0.9 to 1.14. Synonymous variants: 70 observed, 72.5 expected, observed/expected ratio (o/e) 0.97, 90% interval 0.8 to 1.18.
Gene-disease validity (ClinGen):
ClinGen rates the evidence that MCFD2 causes each of these diseases.
factor 5 and Factor VIII, combined deficiency of, 2 (autosomal recessive): Definitive.
Homologues: Orthologues: chimpanzee MCFD2 (100% identical), macaque MCFD2 (99% identical), dog MCFD2 (92% identical), pig MCFD2 (90% identical), rat Mcfd2 (86% identical), guinea pig MCFD2 (83% identical), mouse Mcfd2 (82% identical), tropical clawed frog mcfd2 (60% identical), zebrafish mcfd2 (59% identical), Drosophila melanogaster CG12817 (28% identical). Paralogues in human: CGREF1 (28% identical).
Diseases named in the same sentence as MCFD2 in open-access papers:
MCFD2 is named in the same sentence as 11 diseases in open-access papers, as found by Europe PMC text mining. Sharing a sentence is not in itself a finding about the gene and the disease. The quoted sentences say what the papers report.
coagulation disorder (2 papers, 2023 to 2025). "This will help us know if those with mutations in LMAN or MCFD2 or their family members are predisposed to other coagulation disorders." (PMID 41040772, 2025). "Combined deficiency of coagulation factors V and VIII (F5F8D) is an autosomal recessive coagulation disorder caused by mutations in LMAN1 or MCFD2." (PMID 37978530, 2023).
bleeding disorder (1 paper, 2020). "In humans, genetic deletion of either subunit of a cargo receptor complex, LMAN1/MCFD2, results in a rare bleeding disorder due to the impaired secretion of coagulation factors V and VIII, with a similar phenotype in Lman1-/-and MCFD2-/- mice." (PMID 31978056, 2020).
emphysema (1 paper, 2022). "Mild decreases in AAT levels in LMAN1 and MCFD2 deficient male mice are insufficient to cause AATD symptoms such as COPD and emphysema." (PMID 35322856, 2022).
lung adenocarcinoma (1 paper, 2023). A carcinoma that arises from the lung and is characterized by the presence of malignant glandular epithelial cells. "The results showed that, compared with normal samples, GMPR was under-expressed in tumors, MRPL13 was overexpressed in lung adenocarcinoma, while the expression of MCFD2 and SALL2 between normal lung tissue and lung adenocarcinoma tissue was not different." (PMID 37946181, 2023).
Obesity (1 paper, 2024). Accumulation of substantial excess body fat. "This analysis showed that some proteins, such as COL1A1, COL6A3, FABP4, LEP, LGALS1, and THBS4, are obesity-specific, and GDF15, LPL, MCFD2, REG1A, REG1B, and TCN2 are T2D-specific." (PMID 38732002, 2024).
oral cancer (1 paper, 2023). "Recent studies have shown that MCFD2 is involved in the development of oral cancer, and its expression level in oral cancer cells is significantly higher than in normal cells." (PMID 37946181, 2023).
Thrombocytopenia (1 paper, 2024). A reduction in the number of circulating thrombocytes. "Taken together, these results suggest that the thrombocytopenia observed in Lman1–/– mice results from a potentially novel LMAN1-specific (but MCFD2 independent) function, affecting MK/platelet differentiation or survival." (PMID 39499573, 2024). "LMAN1/MCFD2 double deficient mice exhibited thrombocytopenia, with platelet counts indistinguishable from Lman1–/– mice." (PMID 39499573, 2024). "We now report that LMAN1-deficient, but not MCFD2-deficient mice, exhibit thrombocytopenia and that mice with combined deficiency of LMAN1 and MCFD2 exhibit thrombocytopenia indistinguishable from that in LMAN1-deficient mice." (PMID 39499573, 2024). "Surprisingly, mice deleted for Mcfd2 did not exhibit thrombocytopenia." (PMID 39499573, 2024).
cancer (2 papers, 2022 to 2025). A tumor composed of atypical neoplastic, often pleomorphic cells that invade other tissues. "The second case corresponded to an ER-Golgi protein, encoded by Mcfd2, that plays an important role in controlling stem cell pluripotency and is involved in cancer progression and metastasis." (PMID 36430209, 2022). "Based on the ceRNA hypothesis, our study identified putative downstream mRNAs regulated by miRNAs, such as FGF2, MCFD2, and PIK3R1, which are often reported to exert oncogenic functions in various cancers, consistent with the findings of most previous studies." (PMID 41141624, 2025).
hematologic disorder (1 paper, 2021). A disease involving the hematopoietic system. "Another protein related to hematologic disorders, the multiple coagulation factor deficiency protein 2 (MCFD2), was found exclusively in the predatory venom, suggesting that this venom might have hemorrhagic properties." (PMID 34564647, 2021).
tumor (1 paper, 2023). "The results of single-cell sequencing revealed a significant upregulation of MCFD2 and MRPL13 expression in macrophages, vital cellular components in tumor microenvironments." (PMID 37946181, 2023).
MCFD2 also shares sentences with these, for which no sentence is quoted: glioma (1 paper).